AGR2 (anterior gradient 2, protein disulphide isomerase family member)
Diseases named in the same sentence as AGR2 in open-access papers (continued):
Sharing a sentence is not in itself a finding about the gene and the disease.
cancer (continued). "This suggests that AGR2 functions in the wider dissemination of cancer cells after exiting the prostate." (PMID 38595814, 2024). "Potential cancer promoting effects of AGR2 upregulation include a stimulating role on cell proliferation, migration, epithelial–mesenchymal transition, invasion, and chemoresistance." (PMID 39533806, 2024). "Previous studies have linked AGR2, specifically extracellular AGR2, to epithelial–mesenchymal transition (EMT) and increased migration and invasion of cancer cells." (PMID 39727484, 2024). "Monoclonal antibodies specifically targeting the extracellular AGR2 have shown promising results in human cancers." (PMID 38822246, 2024). "Another substance, increased LINC00460 expression, can inhibit miR-342-3p, which can lead to the upregulation of AGR2, thus promoting cancer invasion." (PMID 39062458, 2024). "In cancers, AGR2 is frequently overexpressed, particularly in prostate and gastrointestinal cancers." (PMID 39062458, 2024). "On the other hand, AGR2 is overexpressed, which reduces the vulnerability of cancer cells and contributes to the development of drug resistance." (PMID 39062458, 2024). "We posit that AGR2 has already paved the way for novel discoveries regarding its therapeutic role in cancer." (PMID 39062458, 2024). "This complex can upregulate AGR2 transcription by influencing epigenetic modification of the AGR2 promoter region and therefore promote cancer development." (PMID 39156959, 2024). "ER localization is essential for AGR2 to function effectively, with its localization playing a crucial role in cancer cell survival and metastatic pathways." (PMID 39062458, 2024). "Techniques such as methylation-specific PCR have been employed to detect AGR2 expression in cancer cells, revealing significant expression levels in such cells." (PMID 39062458, 2024). "Previous studies have detected AGR2 mRNA in matched normal tissue from cancer patients in a select set of tissues, but a comprehensive examination of normal tissue expression has not been conducted to date." (PMID 39727484, 2024). "Conversely, other studies have demonstrated that the overexpression of AGR2 can trigger cancer progression." (PMID 39062458, 2024). "Intracellular AGR2 can promote the growth and survival of cancer cells, while extracellular AGR2 can be defined as a microenvironment regulator that makes cancer cells more aggressive." (PMID 37197416, 2023). "Previous research has shown that intracellular AGR2 (iAGR2) can promote cancer cell growth and survival and that extracellular AGR2 (eAGR2) can be defined as a microenvironment regulator that makes cancer cells more aggressive." (PMID 36899352, 2023). "Based on this evidence, we suggest that AGR2 secreted into CM in response to sorafenib stimulation plays an oncogenic role in HCC cancer progression." (PMID 36899352, 2023). "AGR2 has been detected in different cancer types and is highly expressed in liver, breast, pancreas and bladder cancer tissues compared with healthy tissues." (PMID 36899352, 2023). "Judging by studies conducted on human cancer cell lines, the AGR2 effect on EMT, migration and invasion abilities depends on the form of the protein, intracellular or extracellular." (PMID 37175601, 2023). "AGR2 was found to trigger cancer metastasis in animal models, and the interaction of ATP-dependent RNA helicase DDX3X with AGR2 has been characterized at protein level." (PMID 37371098, 2023). "AGR2 has been demonstrated to have numerous domains, contributing to diverse functions in cancer cells." (PMID 36899352, 2023). "It is necessary to explore the role of induced AGR2 expression in adult mammals, particularly in light of eAGR2 expression as a marker in different human carcinomas." (PMID 37175601, 2023).
cancer (continued). "Compared to other luminal cell subtypes, basal/intermediate cell subtypes C8 has a higher expression level of AGR2, which was reported to be overexpressed in PCa compared to benign tissue and played an essential role in cancer spread." (PMID 36712886, 2022). "AGR2 as a PDI family member was shown to be associated with the development of several diseases, including cancer." (PMID 34929376, 2022). "The first role of ER-based AGR2 is to buffer ER proteostasis in high metabolic and proliferating cancer cells as well as to control protein secretion as widely reviewed previously." (PMID 35965326, 2022). "In total, 19 signaling pathways were identified, with pathways in cancer and proteoglycans in cancer as the two most prominent hits, indicating that AGR2 downregulation and TGF-β exposure, either alone or combined, provide protumoric and prometastatic signals." (PMID 36142758, 2022). "Among the 32 cancer types that are available in the PanCancer Atlas project of TCGA, only part of them displays a consistent expression of AGR2 and AGR3." (PMID 35857928, 2022). "AGR2 is also considered a potential cancer biomarker in pancreatic, breast, lung, and colorectal cancers." (PMID 35600368, 2022). "The precise role of AGR2 in a number of these processes still evades full understanding, although substantial evidence points towards its important role in cancer progression and metastasis." (PMID 36142758, 2022). "Elevated AGR2 expression across several cancers has been shown to support the growth of cancer cells through multiple pathways such as Wnt/β-catenin and Hippo signaling pathway." (PMID 35965326, 2022). "AGR2 is a member of the disulfide isomerase family, is highly expressed in multiple cancers, and promotes cancer metastasis." (PMID 35055132, 2022). "The AGR2 gene extinction pattern appears to be correlated with that of several cancer genes, reinforcing the participation of this protein in cancer phenotypes." (PMID 35857928, 2022). "AGR2 is the most studied PDI member in the cancer setting and therefore, researchers have a keen interest in targeting this molecule for cancer treatment." (PMID 35965326, 2022). "Base on recent investigations indicating the function of AGR2 to cancer progression, we aimed to confirm regulatory effect of circADAMTS6 on AGR2 expression." (PMID 35962061, 2022). "It has also been found that PDI proteins including AGR2 refluxed to the cytosol in cancer and gain new functions through a phenomenon called ER-to-cytosol Signaling (ERCYS)." (PMID 35965326, 2022). "It has been elucidated that extracellularly localized AGR2 contributed to several hallmarks of cancer such as ECM remodeling, inflammation, metastasis, cell proliferation and angiogenesis." (PMID 35965326, 2022). "There were also multiple interactomics studies aimed at expanding the search for AGR2 interaction partners to further understand the role of AGR2 in cancer." (PMID 35965326, 2022). "Subsequent OMICS screening identified AGR2 as being overexpressed in the human cancers of the prostate, lung, stomach, ovarian, pancreas, esophagus, as well as head and neck." (PMID 35965326, 2022). "AGR2 is over-expressed in a diverse set of human cancers including breast, prostate, pancreatic, liver, ovarian, esophagus, and lung cancers." (PMID 34200338, 2021). "AGR2 and TFF1, for example, are both estrogen-responsive gene elements that have been associated with a variety of different cancers." (PMID 33883548, 2021). "Agr2 has conserved roles in tissue development and regeneration and is positively correlated with human cancers." (PMID 34104113, 2021). "It has been widely reported that AGR2 is involved in the modulation of drug sensitivity in several cancers." (PMID 33413231, 2021). "On the contrary, the presence of AGR2 in the extracellular milieu, especially in cancer cells, implies that AGR2 exerts pro-oncogenic effects via diverse mechanism(s)." (PMID 33717413, 2021).
cancer (continued). "If PENK can prevent cancer cell de-differentiation and maintain high eAGR2 expression, then anti-AGR2 immunotherapy would be a potentially effective therapy." (PMID 34911496, 2021). "AGR2 has been shown to participate in various cancer signalling pathways including Hippo, EGFR, EsR, cyclin D1, Src, c-Myc, survivin, aryl hydrocarbon receptor (AhR) and transforming growth factor-beta (TGF-β)." (PMID 34452625, 2021). "AGR2, predominantly localized in the endoplasmic reticulum (ER), is also a secreted protein detected in the extracellular compartment in multiple cancers." (PMID 33413231, 2021). "An increasing body of literature reveals the emerging biological roles of AGR2 in disease processes, e.g., inflammatory bowel diseases, cancer development and progression, and responses to chemotherapeutics." (PMID 34679944, 2021). "Anterior gradient 2 (AGR2) is a protein disulfide isomerase over-expressed in numerous types of cancer." (PMID 33717413, 2021). "High AGR2 protein levels are detected in serum and/or plasma samples of lung, prostate, and ovarian cancer patients in comparison to healthy controls suggesting AGR2 as a promising cancer serum biomarker." (PMID 34567804, 2021). "Previous studies have suggested that AGR2 promotes cancer occurrence by increasing cellular growth and downregulating cell apoptosis in different types of cancers." (PMID 34632938, 2021). "The paper shows significantly increased concentrations of AGR2 protein in plasma from cancer patients relative to normal controls." (PMID 34200338, 2021). "In vitro and in vivo studies showed that AGR2-targeting monoclonal antibody, selective peptide, and micro RNA can inhibit cancer cell growth and migration and enhance drug sensitivity." (PMID 33413231, 2021). "The plasma concentration of AGR2 was found significantly higher in patients with EOC than in patients free from cancer." (PMID 34452625, 2021). "Of these overlapping genes, several have been implicated in cancer migration/invasion or metastasis, including EPHB6, AGR2, RAB37, CST1, and B4GALNT3." (PMID 34270616, 2021). "In the pancreas, Agr2 plays an important role in cancer cell growth and survival, and the expression and secretion of Agr2 is increased during pancreatic tumorigenesis." (PMID 34104113, 2021). "AGR2 was also identified as an oncogene in multiple cancers, including the pancreatic, colorectal, and gastric cancers." (PMID 34632938, 2021). "Many cancers including prostate, lung, and ovarian secrete a protein disulfide isomerase protein named AGR2 that has been previously detected in urine and plasma using mass spectrometry." (PMID 34200338, 2021). "The elevated AGR2 expression was indicative of cancer cell differentiation induced by PENK in adenocarcinoma cells." (PMID 34911496, 2021). "On the basis of previous studies of NANOG regulators in various cancers, we chose the following protein regulators for further analysis: AGR2, KLF4, NOTCH1, OCT4, and SOX2." (PMID 32733958, 2020). "We also discussed the possible mechanisms of AGR2 secretion as well as deliberating the functional impacts of AGR2 in cancer settings." (PMID 33005802, 2020). "In vitro, AGR2 silencing by siRNA knockdown showed a decrease in cancer cell proliferation and invasion and increased gemcitabine sensitivity of resistant cells." (PMID 32024004, 2020). "There are emerging evidences that describe the gain-of-function activities of the extracellular AGR2, particularly in cancer development." (PMID 33005802, 2020). "Analysis of AGR2 mRNA isoforms expression using the same datasets demonstrated that AGR2-203 was the isoform predominantly expressed across different cancer types." (PMID 33005802, 2020). "Another NANOG regulator, AGR2, is involved in tumorigenesis and progression of multiple human cancers." (PMID 32733958, 2020). "For example, it was shown that the AGR2 overexpression exhibited enhanced cancer cell proliferation and metastasis as well as promoting cells survival." (PMID 33005802, 2020).
cancer (continued). "Last, we deliberate the current therapeutic strategies and posit the potential use AGR2, as a prognosis and diagnosis marker in cancer." (PMID 33005802, 2020). "This is the first study that showed such promising result of antibody-based therapy targeting AGR2, suggesting that this molecule is an important target in cancer development." (PMID 33005802, 2020). "Analysis of The Cancer Genome Atlas (TCGA) PanCancer Atlas studies showed that AGR2 were mainly amplified in the cancer landscape." (PMID 33005802, 2020). "In recent years, there are accumulating studies that described the presence of AGR2 in the extracellular environment, particularly in the cancer settings." (PMID 33005802, 2020). "AGR2 is found elevated in numerous types of cancer and it has been reported as a novel biomarker with a potential oncogenic role." (PMID 32493835, 2020). "In human cancer models, AGR2 was highly expressed across multiple cancer types and its elevated expression is associated also associated with increased cancer cell fitness." (PMID 33005802, 2020). "Consistent with this, researchers observed an enhanced expression of ER-resident AGR2 in many cancer types." (PMID 33005802, 2020). "Here, we summarized all in-vitro studies that described the presence of AGR2 in the extracellular environment of cancer cells." (PMID 33005802, 2020). "The AGR2 protein was shown to affect drug resistance in cancer cells that can resist radiotherapy and chemotherapy." (PMID 31247903, 2019). "In the present study, we provided a novel explanation that proteasome inhibition resulted in a significant decrease of AGR2 in cancer cells." (PMID 30647455, 2019). "The different strategies used to therapeutically target AGR2-positive cancer cells are evaluated in light of the current evidence." (PMID 31247903, 2019). "Mechanistically, hnRNPL-LINC02273 formed a complex which activated AGR2 transcription and promoted cancer metastasis." (PMID 31856843, 2019). "To demonstrate the effect of AGR2 secreted by cancer cells on fibroblasts organization and for morphological observation, we treated NIH3T3 cells with conditioned medium (CM) collected after 5 days of MCF7, H460 and SKOV3 cultures for 24 h separately." (PMID 31710263, 2019). "In our study, we reported that MCF7 and H460 cancer cell secreted AGR2 linearized NIH3T3 fibroblasts led to the formation of complex structures, which did not occur when cells were treated with SKOV3 CM." (PMID 31710263, 2019). "In contrast, AGR2 expression differs between cancer and normal cells in subcellular localization, eAGR2 vs. iAGR2." (PMID 31303962, 2019). "In conclusion, the novel finding of this study is to explore the regulatory mechanism by proteasome inhibitors on AGR2 expression, particularly to explain the AGR2 ubiquitylation and autophagic degradation in cancer cells." (PMID 30647455, 2019). "The high expression of AGR2 has also been detected in many cancers, including those arising in the breast, respiratory, reproductive, urinary, digestive and endocrine systems." (PMID 31247903, 2019). "In the IHC evaluation of biliary tract tumors, IHC similarly detected AGR2 expression in ductal epithelial cells in 95 out of 100 cancer tissues of the biliary tract." (PMID 31247903, 2019). "In the present study, we aimed to delineate the mechanisms that facilitate AGR2 degradation, leading to the enhanced effectiveness of cancer therapy." (PMID 30647455, 2019). "By contrast, the secreted AGR2 protein from prostate primary cancer cells 10-076 CP and the adenocarcinoma cells LuCaP was shown to induce apoptosis in normal prostate stromal cells." (PMID 31247903, 2019).
cancer (continued). "In contrast to MDK, expression of AGR2 is induced by androgens and was found to be inversely correlated to cancer-specific survival." (PMID 31877738, 2019). "Correspondingly, the analysis of the data collected from the Oncomine Cancer Microarray Database showed that the AGR2 expression level increased in human epidermal growth factor receptor 2 (HER2)-positive breast tumors." (PMID 31247903, 2019). "Comparing AGR2 protein levels in 111 primary lung AdC patient samples with 46 non-cancer samples revealed a significantly higher expression in the AdC samples." (PMID 31247903, 2019). "Overexpression of AGR2 exhibited enhanced cancer cell adhesion to a plastic substratum and extracellular AGR2 enhanced the rate of cancer cell attachment." (PMID 31856843, 2019). "Significant decrease in AGR2 gene expression was noted with Grade 3 and Serous cancers compared with Grade 1 endometrioid cancers." (PMID 30140383, 2018). "An ideal biomarker should have properties to distinguish cancer cells from healthy cells and AGR2 can do it via localization and secretion." (PMID 30544619, 2018). "Our results indicate that recombinant AGR2 increases colony formation in both cancer cell lines (p<0.05)." (PMID 29937991, 2018). "Although a metastatic role for AGR2 in EC is yet to be demonstrated, overexpressing AGR2 or added recombinant AGR2 in culture medium significantly increased proliferation in endometrial derived cancer cell lines." (PMID 30140383, 2018). "Since secreted AGR2 is elevated in patients with cancer (up to 1,000 ng/ml), we sought to develop a novel capture reagent that is able to detect within the range of 1 to 1,000 ng/ml." (PMID 29937991, 2018). "Binding of H10 to AGR2 diminishes AGR2-dependent cell migration and cytotoxicity in the cancer cell lines studied in this report." (PMID 29937991, 2018). "AGR2 can also be secreted and is detected in extracellular fluids; hence AGR2 protein has been proposed as a compelling biomarker for cancer detection and/or follow-up." (PMID 30140383, 2018). "High expression of Agr2 has been identified in several human cancer cells, and it is considered to be a pro-oncogenic factor." (PMID 29760650, 2018). "This allows scientific information acquired on AGR2 and EpCAM pathway regulation to be translated into novel therapeutics that target the AGR2:EpCAM axis for improved cancer management." (PMID 29339412, 2018). "Increased levels of extracellular AGR2 (eAGR2) have been correlated with poor prognosis in cancer patients, making it a potential biomarker." (PMID 29937991, 2018). "The second paradigm maintains that the normal cell migration-promoting function of AGR2 that mediates the regeneration of limb of amphibian is exploited as an oncogenic signal during cancer progression." (PMID 29339412, 2018). "Recent data has further highlighted an extracellular role for AGR2 in promoting cancer growth and complex organoid structures." (PMID 29339412, 2018). "AGR2 has been reported to be a prognostic marker in several hormonally-regulated cancers such as those of breast, prostate and ovary, where it is involved in drug resistance and metastatic growth." (PMID 30140383, 2018). "The expression of AGR2 was analyzed in cancer cell lines exposed to TGF-β alone or to combined treatment with TGF-β and the Erk1/2 inhibitor PD98059 or the TGF-β receptor specific inhibitor SB431542." (PMID 28810836, 2017). "Our initial cohort study indicated that urinary AGR2 was able to differentiate prostate cancer from non-cancer urine with an AUC = 0.75." (PMID 29254211, 2017). "For example, AGR2 (anterior gradient 2) is produced in relatively high abundance by cancer epithelial cells." (PMID 29254211, 2017).